Y_RNA (Y RNA )
Gene: Miscellaneous RNA gene on chromosome 12 (92,170,353 to 92,170,453, reverse strand). Ensembl gene ENSG00000199895.
Homologues: Orthologues: chimpanzee Y_RNA (99% identical), macaque Y_RNA (97% identical). Paralogues in human: Y_RNA (92% identical), Y_RNA (91% identical), RNY3 (90% identical), Y_RNA (90% identical), RNY3P1 (89% identical), Y_RNA (89% identical), Y_RNA (88% identical), Y_RNA (87% identical), Y_RNA (86% identical), RNY3P14 (85% identical), RNY3P5 (85% identical), Y_RNA (85% identical), and 98 more.